DUOXA2 (dual oxidase maturation factor 2)
Description:
Required for the maturation and transport of functional DUOX2 from the endoplasmic reticulum to the plasma membrane. Recruits DUOX2 to the apical cell membrane.
Synonyms: SIMNIPHOM; TDH5
Tractability: Antibody: its Gene Ontology location is reachable by antibodies, with high confidence; UniProt predicts a signal peptide or a membrane-spanning region.
Gene: Protein-coding gene on chromosome 15 (45,114,325 to 45,118,421, forward strand). Ensembl gene ENSG00000140274.
Subcellular location: Endoplasmic reticulum membrane; Apical cell membrane
Pathways (Reactome):
Metabolism: Thyroxine biosynthesis
Gene Ontology:
Molecular function: enzyme binding; protein binding
Biological process: hydrogen peroxide biosynthetic process; intracellular protein localization; positive regulation of cell motility; positive regulation of hydrogen peroxide biosynthetic process; protein localization to plasma membrane; protein maturation; regulation of thyroid hormone generation; protein transport
Cellular component: apical part of cell; apical plasma membrane; cell leading edge; cytosol; endoplasmic reticulum; endoplasmic reticulum membrane; NADPH oxidase complex; plasma membrane; membrane
Genetic constraint (gnomAD): Loss-of-function variants: 22 observed, 27.09 expected, observed/expected ratio (o/e) 0.81, 90% interval 0.58 to 1.16. The upper end of that interval is the gene's LOEUF score, 1.16, which puts it in group 5 of 6, group 1 being the genes least tolerant of losing a copy. Missense variants: 481 observed, 432.6 expected, observed/expected ratio (o/e) 1.11, 90% interval 1.03 to 1.2. Synonymous variants: 188 observed, 189.61 expected, observed/expected ratio (o/e) 0.99, 90% interval 0.88 to 1.12.
Homologues: Orthologues: chimpanzee DUOXA2 (99% identical), macaque DUOXA2 (95% identical), pig DUOXA2 (82% identical), guinea pig DUOXA2 (78% identical), mouse Duoxa2 (78% identical), rat Duoxa2 (78% identical), rabbit DUOXA2 (76% identical), tropical clawed frog duoxa1 (38% identical), zebrafish duox2 (34% identical), Drosophila melanogaster mol (29% identical), Caenorhabditis elegans doxa-1 (28% identical). Paralogues in human: DUOXA1 (54% identical).
Diseases named in the same sentence as DUOXA2 in open-access papers:
DUOXA2 is named in the same sentence as 31 diseases in open-access papers, as found by Europe PMC text mining. Sharing a sentence is not in itself a finding about the gene and the disease. The quoted sentences say what the papers report.
congenital hypothyroidism (11 papers, 2016 to 2026). A thyroid hormone deficiency present from birth. "Although DUOXA2 variants typically present with congenital hypothyroidism, phenotypic variability has been reported." (PMID 42256320, 2026). "Mutations in theDUOX2 and DUOXA2 genes have been described inpatients with congenital hypothyroidism in humans." (PMID 41553842, 2026). "Whereas bi-allelic mutations in DUOX2 and DUOXA2 cause congenital hypothyroidism, heterozygous DUOX2 variants have been implicated in inflammatory bowel disease (IBD)." (PMID 36166305, 2022). "Congenital hypothyroidism happened with the genetic defect of DUOXA2 causing the damage of H2O2 production system." (PMID 34493277, 2021). "DUOX2/DUOXA2 defects can cause congenital hypothyroidism (CH), but it is unknown whether DUOX1/DUOXA1 mutations can also cause CH." (PMID 31428054, 2019). "Loss-of-function mutations in DUOX2 or DUOXA2 genes disrupt H2O2 generation, impairing thyroid hormone synthesis and resulting in congenital hypothyroidism." (PMID 40362701, 2025). "The coexistence of mutations in the dual oxidase maturation factor 2 (DUOXA2) and dual oxidase 2 (DUOX2) genes is rarely identified in congenital hypothyroidism (CH)." (PMID 26758695, 2016). "Mutations in the DUOXA2, DUOX2, and TPO genes are responsible for thyroid dyshormonogenesis and goitrous congenital hypothyroidism (GCH)." (PMID 26758695, 2016). "The dual oxidase maturation factor 2 (DUOXA2) and dual oxidase 2 (DUOX2) genes are rarely identified in congenital hypothyroidism (CH)." (PMID 26758695, 2016).
hypothyroidism (10 papers, 2014 to 2025). Abnormally low levels of thyroid hormone. "Since DUOX2 variants are found at high frequencies among healthy populations, it has been postulated that DUOX2 and DUOXA2 mutations may predispose to hypothyroidism in the setting of genetic or environmental modulators but are not directly causative." (PMID 39413214, 2024). "Indeed, most of the studies on DUOXA1 and DUOXA2 revolve around their function in the thyroid and hormone biosynthesis and, not surprisingly, natural mutations in the DUOXA2 gene have been linked to hypothyroidism." (PMID 24410844, 2014). "This concept finds support in the established genetics of CH, where variations in genes like DUOX2 and DUOXA2 can present as either PCH or TCH hypothyroidism." (PMID 41480151, 2025). "Genes related to TH biogenesis show a normal response to TSH stimulation in hypothyroidism, including Tpo, Pendrin, Tshr, Nis, Mct8, Duox1, Duox2, Duoxa1, and Duoxa2." (PMID 35326426, 2022). "Further studies are needed to determine the duration of this early overt hypothyroidism, which has previously been reported in association with DUOX2 or DUOXA2 mutations and which eventually resolves." (PMID 31044655, 2019). "Defects in the DUOX2/DUOXA2 heterodimer lead to hypothyroidism and goiter." (PMID 26758695, 2016).
thyroid dyshormonogenesis (8 papers, 2016 to 2024). "The remaining two variants included one upstream variant at the MSMB locus that was annotated as pathogenic for hereditary prostate cancer, as well as one stop-gain variant within DUOXA2 that was annotated as pathogenic for thyroid dyshormonogenesis." (PMID 27356984, 2016). "To determine the inheritance mode of CH caused by thyroid dyshormonogenesis, we analyzed 22 family trios, in which the probands carried compound heterozygous mutations in genes involved in thyroid hormone synthesis (DUOX2, DUOXA2, TPO and TG)." (PMID 29650690, 2018). "In addition, 10%–15% of cases are caused by thyroid dyshormonogenesis, which is associated with mutations in thyroid DUOX2, DUOXA2, TG, and TPO." (PMID 37252044, 2023).
colorectal cancer (6 papers, 2015 to 2024). A primary or metastatic malignant neoplasm that affects the colon or rectum. "Expression levels of both DUOX2 and DUOXA2 have been reported to be up-regulated in association with iUC, and in UC-associated colorectal dysplasia and colorectal cancer and are involved specifically in inflammation and regulated on a crypt-by-crypt basis in UC." (PMID 25991924, 2015). "DUOX2 is upregulated in inflammatory bowel disease and colorectal cancers and, alongside DUOXA2, is a primary driver of H2O2 production in mucosal tissues, which may contribute to chronic inflammation and reactive oxygen species (ROS)-related DNA damage." (PMID 34700376, 2021). "In addition to its role in the persistent and recurrent inflammatory of UC, the DUOXA2/DUOX2 pathway is also involved in the development of UC-associated adenomas and colorectal cancer." (PMID 32190668, 2020). "DUOXA2 was maturation factor of an oxidative protein DUOX2, which promotes invasion and metastasis of colorectal cancer." (PMID 36930369, 2023).
ulcerative colitis (5 papers, 2020 to 2025). An inflammatory bowel disease involving the mucosal surface of the large intestine and rectum. "Furthermore, we also found a strong correlation between Veillonella and DUOXA2, a highly expressed gene causing inflammation in ulcerative colitis." (PMID 31992345, 2020).
goiter (4 papers, 2016 to 2021). Enlargement of the thyroid gland usually caused by lack of iodine in the diet, hyperthyroidism, or thyroid nodules. "In the biallelic group, we found that 81.8% (18/22) of cases (16 cases of GIS, 4 cases of goiter, and 2 cases of TD) harbored variants in DUOX2, two GIS cases had DUOXA2 variants, and two TD cases had TSHR variants." (PMID 34539567, 2021). "A novel DUOXA2 missense mutation (I26M) causes goiter that affected H2O2 production but did not alter protein expression levels." (PMID 34493277, 2021).
pancreatic cancer (4 papers, 2013 to 2017). "Duox2 expression detected by Duox S-12 was functionally coupled to the generation of H2O2 in pancreatic cancer cells that expressed Duox2 and its cognate maturation factor DuoxA2." (PMID 23404210, 2013). "DUOX2 expression, unlike that of the DUOX1 homolog, is associated with progression of pancreatic cancer; the pro-inflammatory cytokine IFN-γ triggers Stat1-mediated DUOX2/DUOXA2 up-regulation in pancreatic cancer cell lines, contributing to increased intra- and extracellular ROS production." (PMID 28578276, 2017). "Among its specific interaction partners, DUOX2 requires the maturation factor DUOXA2 for the formation of a functional, H2O2-producing complex; the expression of DUOXA2, like DUOX2, is also up-regulated by IFN-γ exposure in human pancreatic cancer cells." (PMID 27637085, 2016). "We previously reported that several human pancreatic cancer cell lines up-regulate the expression of DUOX2 and DUOXA2 in response to treatment with the pro-inflammatory cytokines IFN-γ and LPS, although to varying degrees." (PMID 27637085, 2016).
inflammatory bowel disease (3 papers, 2021 to 2024). A spectrum of small and large bowel inflammatory diseases of unknown etiology. "For example, inflammatory diseases such as inflammatory bowel disease (IBD) are associated with certain antimicrobial genes like DUOX2 and DUOXA2, and elevated DUOX2 levels in the intestine often indicate increased inflammation and mucosal dysbiosis." (PMID 38101300, 2024).
thyroid (3 papers, 2020 to 2023). "However, mouse models with biallelic inactivation of DUOX2 or DUOXA2 present a normal developed thyroid gland with only thyroid dyshormonogenesis." (PMID 32425884, 2020).
adenoma (2 papers, 2020 to 2025). A neoplasm arising from the epithelium. "Bulk RNA sequencing reveals upregulated Reactive oxygen species (ROS)-inducing enzymes DUOX2 and DUOXA2 in FAP adenomas." (PMID 40280932, 2025).
athyreosis (1 paper, 2020). Athyreosis is a form of thyroid dysgenesis characterized by complete absence of thyroid tissue that results in primary congenital hypothyroidism, a permanent thyroid deficiency that is present from birth. "Among 288 children with TD, 22 of 121 children with athyreosis, 17 of 93 children with ectopia and 15 of 74 children with hypoplasia carried DUOXA2 variants." (PMID 32425884, 2020). "Specifically, a nonsense (p.Y246X) variant in DUOXA2 had an extremely high rate, with a frequency of up to 68 in 377 cases (18.04%), including 20 GIS cases and 48 TD cases (comprising 13 hypoplasia cases, 17 ectopia cases and 18 athyreosis cases)." (PMID 32425884, 2020).
autoimmune hypothyroidism (1 paper, 2019). "Indeed, one maternal DUOXA2 carrier in our cohort developed non-autoimmune hypothyroidism postpartum." (PMID 31044655, 2019).
colon tumor (1 paper, 2020). "DUOXA2, CEACAM7, and the proto-oncogene ADRA1B were downregulated by calcitriol in rectal tumor organoids, but upregulated in colon tumor organoids." (PMID 32824266, 2020).
Crohn disease (1 paper, 2019). A gastrointestinal disorder characterized by chronic inflammation involving all layers of the intestinal wall, noncaseating granulomas affecting the intestinal wall and regional lymph nodes, and transmural fibrosis. "In SAM enteropathy and in Crohn's disease there was increased expression of DUOX2, DUOXA2, lipocalin 2, CEACAM 5 and 7, MUC1, SAA 1, 2 and 4, and CXCL5 genes, and these transcripts were further over-expressed in HIV infection." (PMID 31229436, 2019).
Graves' hyperthyroidism (1 paper, 2023). "The genes related to the antithyroid effects of long-term iodine loading are Slc5a5, Slc26a4, Duox2, and Duoxa2, in addition to Tpo, Dio1, and Slco4a1, which are upregulated in Graves' hyperthyroidism." (PMID 36565031, 2023).
lung carcinoma (1 paper, 2020). "Lung cancer also presents decreased expression of DUOX1 and DUOX2 that iscorrelated with hypermethylation of CpG-rich promoter regions of DUOX genes.Moreover, DUOXA1 and DUOXA2 weredown-regulated in lung cancer cells and lung cancer tissues." (PMID 32453337, 2020).
transient congenital hypothyroidism (1 paper, 2023). A common, self-limiting thyroid disorder seen in preterm infants that is characterized by abnormally low serum levels of thyroxine and free thyroxine with normal serum levels of thyroid stimulating hormone. "These variants of carrier status were located in DUOX2 and DUOXA2 Genetic factors, in particular mutations in DUOX2 and DUOXA2 is a major contributor to the overall increase in the incidence of CH and transient congenital hypothyroidism (TCH)." (PMID 37147621, 2023).
vitiligo (1 paper, 2021). Generalized well circumscribed patches of leukoderma that are generally distributed over symmetric body locations and is due to autoimmune destruction of melanocytes. "The upregulated genes in vitiligo lesional skin include markers of inflammation (such as MARCO, NLRP10, PTGS2, and IL36G), oxidative response genes (DUOXA2), and NK cell receptors (NCR3LG1), revealing presence of activated immune response in vitiligo lesions." (PMID 33815367, 2021).
cancer (2 papers, 2020 to 2025). A tumor composed of atypical neoplastic, often pleomorphic cells that invade other tissues. "Third, in vitro studies demonstrated that IL-17A and duodenal ILC3s induce DUOX2/DUOXA2 expression, with the former specifically upregulating Duox2 protein, thereby driving mitochondrial-independent ROS production and DNA damage, a key mechanism in cancer progression." (PMID 40280932, 2025). "The abnormal expressions of NOS2, DUOX2/DUOXA2, ESR1, EGFR, MYC, and AKT1, which are being discussed in this study, have been confirmed to be related to cancer." (PMID 33299870, 2020).
infection (1 paper, 2011). The state of being infected such as from the introduction of a foreign agent such as serum, vaccine, antigenic substance or organism. "An approximate 12- and 8-fold up-regulation of dual oxidase 2 (DUOX2) and DUOXA2 respectively was observed between the rats that received a secondary parasite challenge and those that received the sham infection." (PMID 21698235, 2011).
tumor (1 paper, 2025). "Both Duox2 and DuoxA2 exhibit overexpression in human pancreatic and colorectal cancer cells, thereby increasing the susceptibility of these cells to tumor progression via the generation of elevated levels of reactive oxygen species (ROS) that promote tumor progression." (PMID 40909948, 2025).
DUOXA2 also shares sentences with these, for which no sentence is quoted: thyroid dysgenesis (5 papers); colitis (2); asthma (1); autism spectrum disorder (1); cystic fibrosis (1); deafness (1); gastric cancer (1); intestinal infection (1); prostate carcinoma (1); rectal tumor (1).